HNRNPDL (heterogeneous nuclear ribonucleoprotein D like)
Description:
Acts as a transcriptional regulator. Promotes transcription repression. Promotes transcription activation in differentiated myotubes (By similarity). Binds to double- and single-stranded DNA sequences. Binds to the transcription suppressor CATR sequence of the COX5B promoter (By similarity). Binds with high affinity to RNA molecules that contain AU-rich elements (AREs) found within the 3'-UTR of many proto-oncogenes and cytokine mRNAs. Binds both to nuclear and cytoplasmic poly(A) mRNAs. Binds to poly(G) and poly(A), but not to poly(U) or poly(C) RNA homopolymers. Binds to the 5'-ACUAGC-3' RNA consensus sequence.
Synonyms: HNRPDL; JKTBP; laAUF1; HNRNP; JKTBP2; LGMD1G; LGMDD3
Tractability: PROTAC: UniProt records ubiquitination sites on it; ubiquitination databases record sites on it; its protein half-life has been measured.
Gene: Protein-coding gene on chromosome 4 (82,422,565 to 82,430,471, reverse strand). Ensembl gene ENSG00000152795.
Subcellular location: Nucleus; Cytoplasm
Subcellular location (Human Protein Atlas): Nucleoplasm
Pathways (Reactome):
Immune System: Gene and protein expression by JAK-STAT signaling after Interleukin-12 stimulation
Gene Ontology:
Molecular function: protein binding; RNA binding; nucleic acid binding
Biological process: regulation of gene expression
Cellular component: cytoplasm; nucleoplasm; nucleus; chromatin; cytosol
Genetic constraint (gnomAD): Loss-of-function variants: 16 observed, 42.29 expected, observed/expected ratio (o/e) 0.38, 90% interval 0.25 to 0.57. The synonymous counts are far from expectation, so gnomAD's model fits this gene poorly and the ratio says little. Missense variants: 540 observed, 504.53 expected, observed/expected ratio (o/e) 1.07, 90% interval 1 to 1.15. Synonymous variants: 298 observed, 188.89 expected, observed/expected ratio (o/e) 1.58, 90% interval 1.43 to 1.74.
Gene-disease validity (ClinGen):
ClinGen rates the evidence that HNRNPDL causes each of these diseases.
muscular dystrophy, limb-girdle, autosomal dominant (autosomal dominant): Definitive. Autosomal dominant form of limb-girdle muscular dystrophy.
Homologues: Orthologues: chimpanzee HNRNPDL (100% identical), macaque HNRNPDL (99% identical), dog HNRNPDL (99% identical), pig HNRNPDL (98% identical), rabbit HNRNPDL (97% identical), guinea pig HNRNPDL (91% identical), tropical clawed frog hnrnpdl (58% identical), zebrafish hnrnpdl (56% identical). Paralogues in human: HNRNPD (48% identical), HNRNPAB (46% identical), MSI2 (27% identical), HNRNPA3 (26% identical), MSI1 (26% identical), HNRNPA1 (25% identical), HNRNPA2B1 (24% identical), HNRNPA1L2 (24% identical), HNRNPA1L3 (24% identical), DAZAP1 (24% identical), HNRNPA0 (22% identical), NUCLEOLIN (21% identical), and 24 more.
Diseases named in the same sentence as HNRNPDL in open-access papers:
HNRNPDL is named in the same sentence as 27 diseases in open-access papers, as found by Europe PMC text mining. Sharing a sentence is not in itself a finding about the gene and the disease. The quoted sentences say what the papers report.
breast carcinoma (2 papers, 2014 to 2015). "A similar reduction of the cisplatin-induced HNRNPDL exon 6 exclusion and exon 8 inclusion after knock-down of SRSF4 was observed in the breast cancer cell line BT549 (not illustrated)." (PMID 25884497, 2015).
depression (2 papers, 2021 to 2023). "A number of individual top biomarkers are known to be modulated by medications in current clinical use for treating depression, such as by lithium (NRG1, PRPS1, CD47), antidepressants (SLC6A4, DOCK10, NRG1, CD47) and the nutraceutical omega-3 fatty acids (GLO1, SLC6A4, CD47, GLS, HNRNPDL)." (PMID 33828235, 2021).
lung carcinoma (2 papers, 2023 to 2025). "HNRNPD and its similar gene HNRNPDL have been reported to be strongly upregulated in various cancers, including lung cancer, and play key roles in inducing tumour growth and metastasis, while TMEM150C is not well studied in cancer biology." (PMID 39909829, 2025). "HNRNPDL exhibited higher activity in T cells of lung cancer, and it has been demonstrated that RNPL regulates T cell differentiation and migration by regulating pre-T cell receptor and chemokine receptor signaling." (PMID 36681772, 2023).
muscular dystrophies (2 papers, 2021 to 2024). "The remaining six families had pathogenic variants in genes usually associated with muscular dystrophies (HNRNPDL, TOR1AIP1, SGCG, COL6A2, CAV3, TRIP4)." (PMID 38982518, 2024). "Mutations in the prion-like domain of hnRNPDL cause muscular dystrophy-like conditions." (PMID 34445083, 2021).
Bethlem myopathy (1 paper, 2022). A usually autosomal dominant inherited movement disorder caused by mutations in the COL6A1, COL6A2, and COL6A3 genes. "Autosomal dominant LGMDs represent about 10–15% of LGMDs and include disorders due to defects of DNAJB6, transportin-3 (TNPO3), HNRNPDL, Calpain-3 (CAPN3), and Bethlem myopathy." (PMID 35309568, 2022).
cancer (4 papers, 2022 to 2025). A tumor composed of atypical neoplastic, often pleomorphic cells that invade other tissues. "Heterogeneous nuclear ribonucleoprotein D-like (hnRNPDL) was strongly downregulated in all investigated groups, except carcinoma luminal B (only 0.5 downregulated)." (PMID 39000458, 2024).
tumor (4 papers, 2019 to 2025). "Consistent with this research, our results indicated that HNRNPDL served as a potent tumor suppressor gene." (PMID 31355251, 2019).
neurological diseases (2 papers, 2020 to 2024). "HNRNPDL and RBM39 function in transcriptional regulation, HNRNPDL and SRSF2 regulate alternative splicing, MPRIP is involved in stress granule formation, CHID1 has a role in pathogen sensing, and KIF21A has been implicated in neurological diseases." (PMID 32380717, 2020).
infection (1 paper, 2020). The state of being infected such as from the introduction of a foreign agent such as serum, vaccine, antigenic substance or organism. "The inclusion of exon 8 targets HNRNPDL for nonsense-mediated decay (NMD), presenting the possibility that by promoting exon 8 inclusion, ZIKVPR infection targets HNRNPDL for degradation." (PMID 32380717, 2020). "Interestingly, however, in DENV2 infection, we determined small but significantly different changes in exon inclusion/exclusion levels in CHID1, SRSF2, HNRNPDL, and RBM39." (PMID 32380717, 2020).
HNRNPDL also shares sentences with these, for which no sentence is quoted: myopathies (2 papers); acute lymphoblastic leukemia (1); autosomal dominant limb-girdle muscular dystrophy type 1G (1); cervical cancer (1); cognitive decline (1); colon cancer (1); Crohn disease (1); endometrial cancer (1); leukemia (1); neurodevelopmental disorder (1); neurogenic muscular atrophy (1); neuromuscular disease (1); prostate carcinoma (1); rheumatic diseases (1); rheumatoid arthritis (1); systemic lupus erythematosus (1); tauopathy (1); ZIKV infection (1).